AFP (alpha fetoprotein)
Diseases named in the same sentence as AFP in open-access papers (continued):
Sharing a sentence is not in itself a finding about the gene and the disease.
tumor (continued). "Therefore, DCP is a promising HCC predictive and prognostic marker, and, when it is combined with AFP, it may complement US in the early tumor detection." (PMID 36831120, 2023). "Moreover, the stratified analysis determined the superiority of the RA approach in different subgroups, especially for patients with tumours < 5 cm or lower AFP, indicating that the RA route may provide more potential benefits at certain stratifications." (PMID 36631744, 2023). "Additionally, Tumor marker AFP showed an elevation to 12.5 ng/ml." (PMID 37950062, 2023). "Besides, in previous clinical studies, the level of AFP may be a surrogate marker of tumor response." (PMID 37937058, 2023). "Additionally, these data provide support to the hypothesis that increasing TAD improves patient outcomes for tumor response, AFP response, and OS in a dose-dependent manner." (PMID 35394152, 2022). "DAA treatment may reduce inflammation and may reveal tumor-derived AFP." (PMID 35020772, 2022). "AFP also exerts a pro-oncogenic priming in both animal and human models of HCC by reducing the FAS/FAS-associated death domain protein (FADD) apoptotic pathway through the modulation of Human Antigen R RNA-binding protein, resulting in the promotion of tumor growth." (PMID 36230554, 2022). "Likewise, the combination therapy may not be recommended for patients with M2 along with a tumor size of 3–5cm, tumor number of two to three, or AFP >400 μg/L because adjuvant sorafenib seemed inadequate to enhance the efficacy of RFA." (PMID 35814378, 2022). "Alternatively, the AFP expression might have originated from undetected yolk sac tumor cells." (PMID 34518930, 2022). "Therefore, more studies are needed to confirm whether AFP can be used as a specific tumor marker for GC to guide clinical practice." (PMID 35710379, 2022). "Similarly, another multicenter study found that a combined model composed of clinical data (AFP, albumin-bilirubin grade, tumor margin, and liver cirrhosis) and three-feature radiomic signatures achieved high prognostic performance in predicting recurrence in post-resection patients." (PMID 36551606, 2022). "However, RFA presented worse survival than repeated hepatectomy in patients with aggressive recurrent HCC, including those with a tumor size greater than 3 cm, an alpha-fetoprotein (AFP) level greater than 200 μg/L, and who relapsed within 2 years following initial resection." (PMID 35814378, 2022). "In addition, we found that AFP level, with or without extrahepatic metastasis, Child-Pugh, tumor number, was associated with the efficacy of lenvatinib." (PMID 36483048, 2022). "Thus, the DCs loaded with rAAV-AFP were more effective than the DCs loaded with the tumor cell lysate, which might be exploited for the development of DC-based vaccines in AFP-positive HCC." (PMID 35619702, 2022). "To test whether the traditional tumour markers could be used for the prediction of risk of GC in EGC and PLGC, we examined the levels of CEA, AFP, and CA19-9 in plasma of patients with EGC (including 129 patients) and PLGC (including 10 patients with gastricism and 101 patients with LGD or HGD)." (PMID 35186077, 2022). "And AFP response phenomenon could be due to the killing of HCC tumor cells during treatment." (PMID 36483039, 2022). "Likewise, primary tumour size is associated with the frequency of serum tumour marker elevations (expression rates) and the extent of elevations of classical serum tumour markers alpha fetoprotein (AFP), beta human chorionic gonadotropin (bHCG) and lactate dehydrogenase (LDH)." (PMID 36358866, 2022). "Interestingly, the cfDNA level was not significantly linked to gender, age, TNM stage, tumor location, or AFP/NSE expression, but it was significantly correlated with CEA and CA125 expression." (PMID 35685424, 2022).
tumor (continued). "Therefore, we examined if the addition of the MobileNetV2_HCC_class as well as the other independent factors (AFP, tumor size, tumor number) to Stage_AJCC could improve their abilities for risk stratification." (PMID 35352293, 2022). "Furthermore, there are many risk factors for postoperative HCC recurrence including postoperative residual tumor tissuett, microvascular invasion, severe cirrhosis, portal hypertension, DNA replication, α-fetoprotein (AFP), and protein-induced by vitamin K absence-II." (PMID 36684155, 2022). "Additionally, well-known predictors of outcome such as tumor characteristics (size and number) and alpha-fetoprotein (AFP) were evaluated to provide a more comprehensive assessment of this population, with the ultimate goal of enhancing treatment selection and patient prognostication." (PMID 35227234, 2022). "Furthermore, the tumor biomarker, AFP, has also been recognized as a reliable predictor for MVI." (PMID 35664790, 2022). "This study shows that circulating tumor DNA, particularly mSEPT9, shows promising diagnostic potential in HCC; however, it is not enough to diagnose HCC independently, and ctDNA combined with conventional assays such as AFP can effectively improve diagnostic performance." (PMID 36348665, 2022). "Because early-stage tumor diagnosis improves options for potentially curative therapy and thereby improves overall survival, AASLD guidelines recommend surveillance in CLD patients at risk for HCC with liver ultrasound (US) and serum alpha-fetoprotein (AFP) test conducted every 6 months." (PMID 36582804, 2022). "Furthermore, serum DLK1 correlated with AFP and tumor size in HCC patients." (PMID 35805898, 2022). "The number and size of the tumor, like in the Milan criteria or Metroticket, are clearly insufficient for prognostication and only the addition of angiopoietin-2 for Milan criteria, or AFP for Metroticket, makes them able to discriminate between low and high risk of the event." (PMID 36158651, 2022). "However, because of the presence of fetal antigens during pregnancy, related tumor markers such as AFP and CA-125 will increase physiologically and fluctuate with gestational weeks, so the diagnosis of pregnancy complicated by borderline tumors is more difficult." (PMID 35912239, 2022). "We did not encounter any association between AFP and tumour burden calculated by SEC." (PMID 35497085, 2022). "It is clear from a clinical standpoint, that tumors that continue to express high levels of AFP despite locoregional therapy have concerning tumor biology, which may warrant more aggressive locoregional therapy, consideration of systemic therapies, as well as avoidance of liver transplantation." (PMID 36290870, 2022). "As expected, among a subset of patients with serum tumor marker (CA 19-9 or AFP) assessed at the time of each liquid biopsy and accessible radiographic imaging, there was a positive correlation between percent change in ctDNA levels with serum tumor markers and tumor dimensions." (PMID 36463294, 2022). "The sensitivity, specificity, positive predictive value, and negative predictive value of TSGF, GP73, and AFP were 90.0 (54/60), 80.0 (96/120), 69.2 (54/78), and 94.1 (96/102), respectively, indicating that the combined detection of tumor markers produced a favorable diagnostic yield." (PMID 35711497, 2022). "Along with AFP response, direct histological tumor response is also a known predictive factor, especially cPR after downstaging therapy as it is associated with a very low recurrence rate of 5.8% at 5 years irrespective of the initial tumor size." (PMID 35529597, 2022). "Moreover, we found abnormal expressed circ_0008043 is closely related to α-fetoprotein (AFP), tumor size, differentiation, and distant metastasis, but not linked to age, sex, and tumor number." (PMID 35220907, 2022). "Thus, AFP promotes the immune system’s tolerance toward the tumor." (PMID 36518320, 2022).
tumor (continued). "Furthermore, we found that the more AFP level declined, the deeper tumor response." (PMID 35016637, 2022). "AFP levels may be raised due to tumor development or regenerated hepatocytes." (PMID 36577761, 2022). "This retrospective study analyzed risk factors for HCC recurrence and death and compared patients’ tumor characteristics and outcomes in groups of Milan, “Up-to-seven,” and Hangzhou criteria, and groups between met and unmet the combinative criteria of “Up-to-seven” and AFP of < 1000 ng/mL." (PMID 35936699, 2022). "However, the tumor marker serum AFP was significantly increased." (PMID 33663127, 2021). "AFP is considered a marker of HCC differentiation and vascular invasion; thus, the measurement of its serum levels pre-LT has been proposed as a potential tool to identify HCC patients with a higher risk of tumor recurrence and poor post-LT survival who should be excluded from transplantation." (PMID 34501381, 2021). "Indeed, high AFP levels indicate an increase in tumor aggressiveness and may, in turn, predict inferior outcomes after both liver resection and transplantation for HCC." (PMID 33670174, 2021). "However, the current clinical use of RFA depends on the experiences based on the traditional tumor characteristics, like tumor size, tumor numbers, and alpha-fetoprotein (AFP), and whether patients will benefit from pretransplant RFA remains controversial." (PMID 34712326, 2021). "Another study on dendritic cells and immunotherapy found that dendritic cell exosomes rich in AFP may trigger an effective antigen-specific anti-tumor immune response and reshape the tumor microenvironment of HCC mice, providing a cell-free vaccine option HCC immunotherapy." (PMID 33854614, 2021). "However, some researchers reported high numbers of Plasmacytoid dendritic cells (pDCs) within tumors correlated with high alpha-fetoprotein levels, more significant vascular invasion, advanced tumor-node-metastasis stage, shorter overall survival, and a higher recurrence rate." (PMID 33568167, 2021). "Importantly, these TCR gene engineered T cells could specifically kill HLA-A2+ AFP+ HepG2 tumor cells, sparing normal hepatocytes in vitro." (PMID 34071188, 2021). "We first evaluated whether IL-17 and AFP can be found in the tumor tissues of patients in Taiwan." (PMID 33865328, 2021). "However, the levels of tumor markers, alpha-fetoprotein, and carcinoembryonic antigen were normal." (PMID 33847652, 2021). "However, the serum levels of AFP returned to normal soon after tumor resection, and their pathological significance remained unknown." (PMID 33607799, 2021). "The following clinical analyses suggested that high EGR1 expression in patients was associated with increased tumor size and advanced TNM staging, and decreased liver function (reflected by increased expression of TBIL, AST and ALT) and LC severity (increased expression of AFP)." (PMID 34409922, 2021). "First, because AFP+ EC is a rare tumor, we could only study a limited number of cases in detail." (PMID 34977100, 2021). "However, if only two parameters of AFP level and tumor number employed (clinical model), the AUC values in the training cohort and the verification cohort were lowered to 0.707 and 0.696, respectively, which were worse off than the nomogram with gadoxetic acid-enhanced MRI features (P < 0.05)." (PMID 34094938, 2021). "Moreover, it has been shown that extremely elevated AFP levels (>1000 ng/mL) before LT is associated with the worst post-LT survivals, regardless of the tumor burden." (PMID 34885087, 2021). "In the multivariate hazards model, maxim tumor size of ≥5 cm, presence of macro-vascular invasion and PD-L1 ≥3.0 remained significantly associated with increased risk of recurrence, while serum AFP ≥200 ng/ml (HR 1.42, 95%CI: 0.91–2.20) was not an independent risk factor." (PMID 35117990, 2021). "YSTs are diagnosed with tumor markers AFP and LDH however they may rarely show α1-antitrypsin." (PMID 33671303, 2021).
tumor (continued). "Therefore, the AFP expression level in tumor tissue was not strictly associated with serum AFP or hepatoid differentiation." (PMID 33996549, 2021). "DCA showed that if the threshold probability was > 5%, using the nomogram to diagnose MVI could be much more beneficial and it was obvious that its net benefit was considerably higher than that of independent clinical tumor diameter, AFP and TB models within 0.3–0.8 of threshold probability." (PMID 34234239, 2021). "In addition to surveillance using imaging, the concomitant use of serum tumor markers, such as alpha-fetoprotein (AFP), has been controversial because serum AFP could be influenced by the degree of necroinflammation in the liver." (PMID 34231046, 2021). "In addition, in SMCC 7721 cells, upregulation of cellular AFP increased the expression of PD-L1 and B7-H4 both in the level of mRNA and protein, which might promote tumor immune escape, possibly via activation of the NF-κB pathway." (PMID 34680245, 2021). "AFP2-11 -HLA-A*24:02 specific TCR transfected T cells could specifically activate and kill AFP2-11 pulsed T2-A24 cells and AFP+ HLA-A*24:02+ tumor cell lines, demonstrating that AFP2-11 epitope can be naturally presented on the surface of AFP+ tumor cell lines." (PMID 34071188, 2021). "In general, serum AFP levels may be associated with HCC tumor mass, but not all HCC patients show high AFP levels, e.g. above 250–400 ng/ml." (PMID 32614912, 2020). "Moreover, AFP could be used for monitoring HCC progression considering that it promotes tumor proliferation and metastasis." (PMID 33297335, 2020). "Thus, screening programs are used for cancer detection in patients at risk for tumor development and usually include ultrasound (US) with or without serum biomarkers, such as alpha-fetoprotein (AFP)." (PMID 32793278, 2020). "In summary, the results of our study showed that compared to TACE, TACE + RFA could be more effective for treating HCC patients with MVI, especially AFP <400 ng/ml, tumor number <3, tumor diameter <5 cm, or PVTT patients because it could hinder tumor progression and increase OS." (PMID 32884569, 2020). "Moreover, CA125 and AFP were undetectable after tumor resection." (PMID 32629665, 2020). "Thus, we excluded AFP from the tumor markers under consideration." (PMID 31218849, 2020). "Levels of circulating G class antibodies to 44 recombinant tumor associated antigens and circulating AFP were measured in the serum of patients with HCC, non-cancerous chronic liver disease (NCCLD) and healthy controls via enzyme-linked immunosorbent assay (ELISA)." (PMID 32374744, 2020). "Even in the present study, NLR was significantly associated with the variables that represented tumor burden in HCC, such as TNM/BCLC stage and AFP/protein induced by vitamin K absence or antagonist-II (PIVKA-II), although the causal relationship between them could not be determined." (PMID 32455607, 2020). "To determine whether other tumor markers are also elevated in serum-derived exosomes, we selected serum and serum-derived exosomes from the non-OC group to measure and compare the levels of common tumor markers such as AFP, CA125, CA153, CA199 and CEA." (PMID 33033528, 2020). "Notably, relative serum levels of miR-193a-5p directly correlated with the patients’ survival and indicated an unfavorable tumor biology since patients with high AFP, larger tumor diameter and undifferentiated tumors displayed a further down-regulation of miR-193a-5p compared to others." (PMID 32960907, 2020). "However, study has shown that the mRNA expression of NEK2 in HCC tissues was lower than adjacent normal tissues, and was associated with larger tumor diameter, higher alpha-fetoprotein (AFP) concentration, higher tumor stage, worse prognosis and shorter survival time." (PMID 33109182, 2020).
tumor (continued). "In our study, AUROC of AFP ratio could also predict tumor response differentiating CR+PR from PD (AUC, 0.833; 95% CI, 0.69–0.98, Figure 4Ai), CR from PR+PD (AUC, 0.764; 95% CI, 62.0–91.0, Figure 4Aii), and CR from PD (AUC, 0.853; 95% CI, 0.70–1.0, Figure 4Aiii)." (PMID 33614488, 2020). "Besides, these patients had smaller tumor size (4.0 vs 8.7 and 8.8 cm, p<0.001), lower serum level of AFP (373.2 vs 1992.6 and 3082.2 ng/mL, p=0.028); and more of them had experienced surgical resection for HCC before ICI treatment (62.9% vs 21.1% and 50.0%, p=0.013)." (PMID 32863270, 2020). "Thus, novel tumor biomarkers should be made to help the clinical diagnosis of AFP-NHCC." (PMID 32190001, 2020). "This study is limited by the built-in shortage of no information of laboratory data (such as alpha-fetoprotein), and radiographic and pathological findings regarding tumor status in the claim database, which impedes the risk factor analysis between recurrence and non-recurrence." (PMID 33598433, 2020). "However, the popular tumor marker, AFP, lacks sensitivity although its specificity is high." (PMID 31898536, 2020). "Therefore, AFP may promote tumor immune escape, leading to HCC tumor growth, metastasis, and recurrence." (PMID 32774373, 2020). "However, the tumor marker (alpha fetoprotein and BHCG) was normal." (PMID 33425202, 2020). "Moreover, we identified a variety of independent risk factors that significantly associated with MVI, namely, as alanine transaminase (ALT), alpha-fetoprotein (AFP), maximal tumor diameter, and tumor capsule, which were then collectively incorporated into the nomogram." (PMID 31632502, 2019). "Finally, we identified VEGF pathway enrichment in AFP-high tumours." (PMID 31285588, 2019). "In addition, the alteration in AFP level was used for early assessment of response so that we could predict tumor burden and biology." (PMID 31416447, 2019). "Interestingly, multivariate analysis revealed that eIF4E intensity in tumours was an independent prognosticator for relapse‐free survival (RFS) and was significantly associated with clinic ‐pathologic features (serum alpha‐fetoprotein level, gamma glutamyl transferase, vascular invasion of HCC)." (PMID 30677218, 2019). "Furthermore, some studies have revealed that the ratio of certain indicators is related to the prognosis of HCC, such as AFP to tumor volume ratio, alkaline phosphatase to lymphocyte ratio, aspartic acid to lymphocyte ratio and neutrophil times γ-glutamyl transpeptidase to lymphocyte ratio, etc.." (PMID 31165038, 2019). "Furthermore, we analyzed the association between NCAPH expression and the clinicopathological characteristics of HCC patients and found that NCAPH expression was positively related to alpha fetoprotein, tumor size, tumor number, portal vein thrombus, TNM stage, and differentiation grade." (PMID 31523845, 2019). "Nevertheless, the results are insufficient to indicate which patients with numerous small tumors are potentially at acceptable risk of tumor recurrence from the transplant eligibility perspective, as the alpha-fetoprotein concentration did not emerge as a significant risk factor." (PMID 31163668, 2019). "Notably, we found that mean AFP and mean tumor volume are top ranked in patients with haplogroup D5 and haplogroup B5, indicating that haplogroup B5 and D5 may play a role in the disease progression of HCC." (PMID 31629170, 2019). "However, the population of MDSC and serum level of AFP correlated to tumor volume still could be well-expressed." (PMID 30783140, 2019). "Moreover, multivariate Cox regression analysis indicated that the expression of FABP4, Alb, AFP, HBsAg, and PVTT were independent risk factors for overall survival, and the expression of FABP4, AFP, GGT, tumor size, and encapsulation were independent risk factors for HCC recurrence." (PMID 29733540, 2018).